PPP2R5C (protein phosphatase 2 regulatory subunit B'gamma)
Description:
The B regulatory subunit might modulate substrate selectivity and catalytic activity, and might also direct the localization of the catalytic enzyme to a particular subcellular compartment. PP2A-PPP2R5C may also regulate the ERK signaling pathway through ERK dephosphorylation.
Synonyms: B56G; PR61G; B56gamma; HJS4
Tractability: Small molecule: a structure with a bound ligand is known; it has a high-quality binding pocket. PROTAC: ubiquitination databases record sites on it; its protein half-life has been measured.
Gene: Protein-coding gene on chromosome 14 (101,761,682 to 101,927,989, forward strand). Ensembl gene ENSG00000078304.
Subcellular location: Nucleus; Chromosome, centromere
Subcellular location (Human Protein Atlas): Cytosol; Nucleoplasm; Golgi apparatus
Pathways (Reactome):
Disease: APC truncation mutants have impaired AXIN binding; AXIN missense mutants destabilize the destruction complex; CTNNB1 S33 mutants aren't phosphorylated; CTNNB1 S37 mutants aren't phosphorylated; CTNNB1 S45 mutants aren't phosphorylated; CTNNB1 T41 mutants aren't phosphorylated; Signaling by GSK3beta mutants; Truncations of AMER1 destabilize the destruction complex
Signal Transduction: Beta-catenin phosphorylation cascade; Degradation of beta-catenin by the destruction complex; Disassembly of the destruction complex and recruitment of AXIN to the membrane; Negative regulation of MAPK pathway; PI5P, PP2A and IER3 Regulate PI3K/AKT Signaling; RAF activation; RHO GTPases Activate Formins
Cell Cycle: Amplification of signal from unattached kinetochores via a MAD2 inhibitory signal; EML4 and NUDC in mitotic spindle formation; Mitotic Prometaphase; Resolution of Sister Chromatid Cohesion; Separation of Sister Chromatids
Immune System: Co-inhibition by CTLA4; Co-stimulation by CD28
Hemostasis: Platelet sensitization by LDL
Gene Ontology:
Molecular function: protein binding; protein phosphatase activator activity; protein phosphatase regulator activity
Biological process: negative regulation of cell population proliferation; proteasome-mediated ubiquitin-dependent protein catabolic process; signal transduction
Cellular component: chromosome, centromeric region; nucleoplasm; nucleus; protein phosphatase type 2A complex; cytosol
Genetic constraint (gnomAD): Loss-of-function variants: 6 observed, 59.87 expected, observed/expected ratio (o/e) 0.1, 90% interval 0.054 to 0.2. The upper end of that interval is the gene's LOEUF score, 0.2, which puts it in group 1 of 6, group 1 being the genes least tolerant of losing a copy. Missense variants: 326 observed, 598.65 expected, observed/expected ratio (o/e) 0.54, 90% interval 0.5 to 0.6. Synonymous variants: 190 observed, 210.59 expected, observed/expected ratio (o/e) 0.9, 90% interval 0.8 to 1.02.
Homologues: Orthologues: chimpanzee PPP2R5C (100% identical), macaque PPP2R5C (99% identical), dog PPP2R5C (96% identical), guinea pig PPP2R5C (94% identical), tropical clawed frog ppp2r5c (89% identical), rat Ppp2r5c (84% identical), mouse Ppp2r5c (84% identical), pig PPP2R5C (83% identical), rabbit PPP2R5C (82% identical), Drosophila melanogaster wrd (65% identical), Caenorhabditis elegans pptr-2 (61% identical), Caenorhabditis elegans pptr-1 (51% identical). Paralogues in human: PPP2R5D (77% identical), PPP2R5E (55% identical), PPP2R5A (55% identical), PPP2R5B (53% identical).
Diseases named in the same sentence as PPP2R5C in open-access papers:
PPP2R5C is named in the same sentence as 40 diseases in open-access papers, as found by Europe PMC text mining. Sharing a sentence is not in itself a finding about the gene and the disease. The quoted sentences say what the papers report.
Intellectual disability (3 papers, 2015 to 2025). "Because mutations in multiple subunits, including PPP2R1A, PPP2R5B, PPP2R5C, and PPP2R5D, have been linked to intellectual disability, future studies will investigate their roles in eCB signaling and related neuropsychiatric disorders." (PMID 40839403, 2025). "Four mTOR-related genes associated with intracranial volume and intellectual disability, namely, PPP2R5A, PPP2R5C, AKT2, and MTOR, are among the top list of positively selected genes in the human lineage." (PMID 37789379, 2023). "We have identified heterozygous missense mutations in PP2A regulatory subunit B family genes PPP2R5B, PPP2R5C and PPP2R5D in individuals with overgrowth and intellectual disability." (PMID 25972378, 2015).
leukemia (3 papers, 2011 to 2025). A malignant (clonal) hematologic disorder, involving hematopoietic stem cells and characterized by the presence of primitive or atypical myeloid or lymphoid cells in the bone marrow and the blood. "Overexpression of PPP2R5C is observed in various leukemias, implicating its involvement in malignant transformation." (PMID 39331630, 2025). "Therefore, it is interesting to analyze the molecular mechanism of PPP2R5C siRNA-mediated cell proliferation suppression in different leukemia cells." (PMID 24004697, 2013).
melanoma (3 papers, 2015 to 2024). A malignant, usually aggressive tumor composed of atypical, neoplastic melanocytes. "A reduction in the expression of PPP2R5A and PPP2R5C, the genes responsible for encoding B56α and B56γ, respectively, was observed in metastatic tissues of melanoma, resulting in the overexpression of C-MYC occurred and the suppression of oncogene-induced senescence." (PMID 38542160, 2024). "In melanomas, there is reduced gene expression of the B56γ subunit encoded by PPP2R5C." (PMID 25699237, 2015).
Autoimmunity (2 papers, 2021 to 2025). The occurrence of an immune reaction against the organism's own cells or tissues. "Of the 28 DMGs, HLA-DPB2, HLA-DRB1, PPP2R5C, and LTF were associated with autoimmunity." (PMID 34539625, 2021). "Interestingly, when |Δβ| ≥ 0.1 (simultaneously p < 0.01), 4 of the 28 DMGs—HLA-DPB2, HLA-DRB1, PPP2R5C, and LTF, which all mapped from more than one CpG site—are all associated with autoimmunity." (PMID 34539625, 2021).
chronic myeloid leukemia (2 papers, 2013 to 2018). "Downregulation of the PPP2R5C gene expression might be considered as a new therapeutic target strategy for chronic myeloid leukemia." (PMID 29444159, 2018).
diabetes (2 papers, 2018 to 2019). "The PPP2R5C (OMIM 601645) gene on 14q32.31 also plays an important role in diabetes development.." (PMID 30212560, 2018).
osteosarcoma (2 papers, 2020 to 2024). A usually aggressive malignant bone-forming mesenchymal neoplasm, predominantly affecting adolescents and young adults. "Similar to MMP-9, the PPP2R5C, a subunit of protein phosphatase 2A, was expressed on TANs, and may also regulate the proliferation of osteosarcoma via PI3K/AKT pathway." (PMID 39582869, 2024). "From the insights of single-cell sequencing, the expressions of PPP2R5C, PPP2R5E, YWHAG, and CREBBP on TANs were significantly related to the metastatic of osteosarcoma, and these genes may play their roles via HIF-1, PI3K-AKT, and JAK-STAT signaling pathways." (PMID 39582869, 2024).
Ataxia (1 paper, 2020). Ataxia refers to impaired coordination of voluntary muscle movement. "More specifically, the PIK3R1 gene was under-expressed in neuronal datasets as well as in fibroblasts and peripheral blood, while AKT2, PPP2R5C, and SPTLC1 were found over-expressed in neuronal and fibroblast datasets of the “ataxia” phenotype." (PMID 32937819, 2020).
chronic hepatitis B (1 paper, 2018). "In order to explore the relationship between PPP2R5C (encoding B56γ) expression and HBV infection, a genomic expression data set of chronic hepatitis B (CHB) patients was employed." (PMID 29988038, 2018).
colorectal cancer (1 paper, 2024). A primary or metastatic malignant neoplasm that affects the colon or rectum. "Currently, there is a lack of research on the relationship between DNA methylation levels of the DAB1, FAM19A5, and PPP2R5C genes and colorectal cancer." (PMID 39199384, 2024).
COVID-19 (1 paper, 2025). A disease caused by infection with severe acute respiratory syndrome coronavirus 2. "The hypermethylated genes with lowest p-values for hospitalized COVID-19 patients at inclusion (T1) and at 6 weeks post-inclusion (T2) versus HCs included NXN, SLC2A12, RAD54L2, GIMAP5, and PPP2R5C, while the top five hypomethylated genes with lowest p-value were, LOC101928650, DLX5." (PMID 41227320, 2025).
esophageal carcinoma (1 paper, 2023). A primary or metastatic malignant neoplasm involving the esophagus. "In addition to CRC, we found that higher PPP2R5C mRNA levels in tumors showed poorer overall survival rates in several other types of cancer, including adrenocortical adenocarcinoma, uveal melanoma, esophageal carcinoma, and kidney carcinoma." (PMID 37430297, 2023).
myeloid leukemia (1 paper, 2011). A clonal proliferation of myeloid cells and their precursors in the bone marrow, peripheral blood, and spleen. "Overexpression of PPP2R5C in T-cell malignancy as well as in myeloid leukemia cells might relate to its proliferation and differentiation." (PMID 21548944, 2011).
myotonic dystrophy type 1 (1 paper, 2024). Steinert disease, also known as myotonic dystrophy type 1, is a muscle disease characterized by myotonia and by multiorgan damage that combines various degrees of muscle weakness, arrhythmia and/or cardiac conduction disorders, cataract, endocrine damage, sleep disorders and baldness. "As reported, many mRNAs exhibit an increased mis-splicing under pathological conditions, while the RNA helicase DDX6 can relieve this mis-splicing event, for example, overexpression of DDX6 can reduce the mis-splicing of Ppp2r5c and IR2 in the patients of myotonic dystrophy type 1 (MD1)." (PMID 38810698, 2024).
Obesity (1 paper, 2019). Accumulation of substantial excess body fat. "Interestingly, PPP2R5C knockout mice have previously been shown to have age-associated obesity, though this is likely due to decreased locomotive capacity caused by a heart defect associated with the model." (PMID 31798691, 2019). "Relative mRNA content of protein phosphatase 2 regulatory subunit B gamma (PPP2R5C) and transcription factor A, mitochondrial (TFAM) in VAT of lean (white) and persons with obesity (gray) via qRT-PCR." (PMID 31798691, 2019).
serous ovarian cancers (1 paper, 2024). "We further investigated cumulative effects of variants using a gene-wide approach and identified three candidate genes in different analyses: CABLES1 and PPP2R5C in high-grade serous ovarian cancers without and with adjustment for FIGO stage, respectively, and FAM35A in the overall EOC analysis." (PMID 38443389, 2024).
Thrombocytopenia (1 paper, 2025). A reduction in the number of circulating thrombocytes. "PPP2R5C interacts with IER3, and the deletion of IER3 can lead to platelet and RBC defects, accompanied by thrombocytopenia." (PMID 39331630, 2025).
tumor (16 papers, 2007 to 2025). "MGMT encodes a DNA repair enzyme, and PPP2R5C encodes the B56γ subunit of the PP2A tumour suppressor." (PMID 38443389, 2024). "PRKACB (HR = 0.586), PPP2R5C (HR = 0.388), and MAPK3 (HR = 0.143) are associated with improved survival, suggesting their higher expression is protective against tumor progression." (PMID 39975150, 2025). "The analysis revealed that the relative expressions of PPP2R5C were downregulated in HCC tumour tissues compared with the normal tissues." (PMID 35811356, 2022). "We therefore directly genotyped the tumour samples of the AGO-OVAR 11 study for the most strongly associated variants in CABLES1 (rs77770767, rs28589524, rs6507532, rs4281829), PPP2R5C (rs2448233, rs59784377, rs3783362, rs79999043), FAM35A (rs11492866) as well as for the MGMT variant rs72845444." (PMID 38443389, 2024). "We then examined the impact of tumour mRNA levels of CABLES1, FAM35A, MGMT and PPP2R5C on PFS in the AGO-OVAR 11 study, and in the publicly available TCGA datasets." (PMID 38443389, 2024). "By comparing tumor versus non-transgenic tissue the genes Mthfd1, Myom1 and Ppp2r5c showed change in direction of gene expression." (PMID 22815814, 2012). "However, when comparing tumor versus transgenic tissue gene Kif26b showed a change in direction and when comparing tumor versus non-transgenic tissue the genes Mthfd1, Myom1 and Ppp2r5c equally differed in direction of gene expression." (PMID 22815814, 2012).
cancer (9 papers, 2006 to 2025). A tumor composed of atypical neoplastic, often pleomorphic cells that invade other tissues. "The results described here suggest that upon PPP2R5C knockdown, cells also increase their glucose uptake, glycolytic rate, and lipid biosynthesis—all of which are metabolic hallmarks for cancer cells." (PMID 26440364, 2015). "HIF1α is known to be frequently up-regulated and functionally relevant in cancers, therefore HIF1α may be a relevant downstream PPP2R5C target in this pathological context." (PMID 26440364, 2015). "In contrast, PPP2R2A was the most deleted gene found in > 20% of samples across 17 cancers, followed by the deletion of SLC2A4 in 16 cancers and five additional genes (FOXO3, PPP2CB, PPP2R2D, PPP2R5C and PPP2R5E) in 15 cancer types." (PMID 32807122, 2020).
infection (2 papers, 2018 to 2024). The state of being infected such as from the introduction of a foreign agent such as serum, vaccine, antigenic substance or organism. "The gene expression levels of HBX and PPP2R5C were higher in the livers of HLC mice with HBV infection than those in mice without infection." (PMID 29988038, 2018).
heart disease (1 paper, 2018). "Multiple genes known or plausibly linked to heart development and post-natal heart disease were found to be differentially methylated in the blood DNA of newborns with TOF including: ABCB1, PPP2R5C, TLR1, SELL, SCN3A, CREM, RUNX and LHX9." (PMID 30212560, 2018).
PPP2R5C also shares sentences with these, for which no sentence is quoted: breast carcinoma (2 papers); colon cancer (2); lung carcinoma (2); adenocarcinoma (1); adenoma (1); Alzheimer disease (1); autism (1); emphysema (1); endometrial carcinoma (1); Hepatitis B (1); Infertility (1); Insulin resistance (1); kidney carcinoma (1); nasopharyngeal carcinoma (1); ovarian carcinoma (1); personality disorder (1); prostate carcinoma (1); Sézary syndrome (1); uveal melanoma (1).